FGF23 (fibroblast growth factor 23)
Diseases named in the same sentence as FGF23 in open-access papers (continued):
Sharing a sentence is not in itself a finding about the gene and the disease.
hypophosphatemic rickets (continued). "However, a direct contribution of FGF23 to the osteoblast differentiation and maturation defects in hypophosphatemic rickets has never been shown." (PMID 37943605, 2023). "Forms of hypophosphatemic rickets independent of FGF23, due to genetic defects of renal tubular phosphate reabsorption such as hypophosphatemic rickets with hypercalciuria (HHRH), are treated with phosphate only, as these diseases are associated with increased renal 1,25(OH)2D synthesis." (PMID 35352187, 2022).
Hypocalcemia (108 papers, 2011 to 2026). An abnormally decreased calcium concentration in the blood. "The RYK gene was previously associated with shortened long bones in the limbs in mice, while FGF23 was associated with subclinical hypocalcemia in dairy cows and 1,25-Dihydroxyvitamin D synthesis." (PMID 39512801, 2024). "Low levels of vitamin D associated with hypocalcemia are known to reduce FGF-23 levels and can directly and indirectly stimulate PTH production." (PMID 33469545, 2020). "Rats fed a low Ca diet showed hypocalcemia and associated decreased plasma FGF23 concentrations, while feeding a high Ca diet to mice increased both, plasma Ca and FGF23 concentrations." (PMID 26870965, 2016). "The final cost of lowering phosphorus is an increase in the levels of FGF23 and hypocalcaemia, this last one causing an increase in the synthesis and liberation of parathyroid hormone (PTH) 19,20." (PMID 27821896, 2016). "The hypocalcemia observed in Wistar rats with normal kidney function, fed with a low-calcium/low–vitamin D diet, was associated with lower FGF23 levels." (PMID 26193703, 2015). "In contrast, hypocalcaemia (calcium deficiency) reduces the circulating concentrations of FGF23." (PMID 30348110, 2018). "Hypocalcemia was associated with decreased plasma FGF23 concentrations in rats." (PMID 26870965, 2016). "First, hypocalcemia, hyperparathyroidism, and vitamin D deficiency could be associated with increased circulating FGF-23 levels and renal functional deterioration." (PMID 25412875, 2014). "Considering that FGF23 inhibits 1,25(OH)2D synthesis, its overexpression can exacerbate hypocalcemia." (PMID 41190261, 2025). "Elevated plasma fibroblast growth factor-23 (FGF23) is activated to counteract reduced phosphate excretion, inhibiting vitamin D synthesis and causing hypocalcaemia." (PMID 38473905, 2024). "Persistent exposure to either hypocalcemia or high FGF-23, conditions which are often simultaneously met in advanced CKD patients, leads to lower expression of FGFR and Kl." (PMID 38785509, 2024). "Synthesis of 1-α-hydroxylase—D3 (or cholecalciferol) increase—is enhanced by PTH and hypocalcemia, while hyperphosphatemia and FGF-23 accelerate D3 degradation." (PMID 38785509, 2024). "The ameliorated increase in PTH secretion in conditions of hypocalcemia can, therefore, be attributed to the artificial introduction of FGF-23 in the milieu of normal cells." (PMID 38785509, 2024). "Calcium is a crucial regulator of FGF23 production, and studies indicate that FGF23 synthesis is impaired in the setting of hypocalcemia." (PMID 38530370, 2024). "High FGF23 inhibits 1,25 dihydroxy vitamin D synthesis and via this pathway reduces calcium absorption in the gut leading to hypocalcaemia." (PMID 37249051, 2023). "Evocalcet with concomitant vitamin D receptor activator demonstrated benefits such that more patients achieved the corrected calcium target and exhibited decreased fibroblast growth factor-23 synthesis; the incidence of hypocalcemia also decreased." (PMID 35176038, 2022). "Subsequently, low calcitriol levels and hypocalcemia induced by increasing FGF23 levels indirectly stimulate PTH synthesis and release in the parathyroid via VDR and CaSR, overriding the inhibitory action of FGF23." (PMID 35269640, 2022). "In turn, excess serum phosphorus increases PTH secretion, as well as results in hypocalcaemia (phosphorus forms complexes with calcium) and stimulates fibroblast growth factor-23 (FGF-23)." (PMID 36672533, 2022). "It is likely that hypocalcemia reduces circulating FGF23 to prevent a decrease in calcitriol, which would worsen a situation of calcium deficiency." (PMID 30909513, 2019). "In a study in which rats fed a low-calcium and low-vitamin D diet, severe hypocalcemia resulted in the decline of FGF-23 levels although serum PTH values were elevated." (PMID 26186634, 2015).
Hypocalcemia (continued). "This latter observation is in line with findings of a recent phosphate enema case report, in which it was shown that FGF-23 only peaks after correction of hypocalcemia." (PMID 25790436, 2015). "Co-administration of anti-resorptives with i.v. iron infusion is one such risk factor—the inhibition of bone resorption and reduced calcium efflux from bone compounds the iron-infused mediated increase in FGF23 and subsequent blunted parathyroid hormone response, thus resulting in hypocalcemia." (PMID 41445551, 2025). "The activity of 1α-hydroxylase (CYP27B1) and/or 24-hydroxylase (CYP24) is increased by parathyroid hormone (PTH), PTH-related peptide (PTHrP), prostaglandins, hypocalcaemia and hypophosphataemia, and inhibited by fibroblast growth factor-23 (FGF23) and by 1,25(OH)2D alone." (PMID 36835987, 2023). "In conclusion, treatment with evocalcet improved the achievement rate of the serum cCa target, decreased FGF23 levels by suppressing FGF23 synthesis, and decreased the incidence of hypocalcemia in the presence of VDRA, demonstrating the additive benefits of the combination therapy in SHPT patients." (PMID 35176038, 2022). "As CKD progresses, the elevation of serum fibroblast growth factor 23 (FGF23) leads to suppression calcitriol production, consequently inducing hypocalcaemia and stimulating parathyroid hormone (PTH) secretion, ultimately resulting in decreased bone mineral density (BMD)." (PMID 32188054, 2020). "Germ-free mice have elevated FGF23, hypocalcemia, and low 1,25D and 24,25D levels." (PMID 29599772, 2018). "This low FGF-23 levels could be acting as a compensatory response to prevent further reductions in vitamin D levels, which could exacerbate the forthcoming hypocalcemia in the late stages of CKD." (PMID 30370270, 2018). "GF mice had high FGF23 with low 1,25D and 24,25D, and hypocalcemia." (PMID 29599772, 2018). "This decrease in FGF23 might be a response that avoids a subsequent reduction in calcitriol, which could exacerbate hypocalcaemia." (PMID 30348110, 2018). "Under severe hypocalcemia, the drop in circulating FGF-23 may raise active form of vitamin D levels and rescue serum calcium levels." (PMID 26186634, 2015). "Calcium positively correlates with FGF-23 under hypocalcemia." (PMID 26186634, 2015). "Hypocalcemia induced by PTX might also contribute to the low circulating FGF-23 levels observed in our PTX+CKD rats." (PMID 26186634, 2015). "In mice, the failure of fructose to induce FGF23 production may be due to the confounding effects of hypocalcaemia that acutely reduces circulating level of FGF23." (PMID 24718641, 2014). "Our previous study found that significantly elevated PTH could not stimulate the expression of FGF23 in 1α-hydroxylase knockout mice with 1,25(OH)2D3 deficiency and hypocalcemia." (PMID 35801203, 2022). "Hypocalcemia is a common complication to kidney failure and therefore on the basis of our present results we propose an additional mechanism behind the resistance of the parathyroid gland to FGF23 in uremia, as the low plasma Ca2+ levels overrule the inhibitory effect of FGF23." (PMID 29063159, 2018). "However, the mechanism by which hypocalcemia lowers FGF-23 remains to be established." (PMID 28194447, 2017). "As a result, low calcitriol levels and hypocalcemia promote PTH synthesis and release via VDR and CaSR in parathyroid, overriding the inhibitory effect of FGF23." (PMID 35269640, 2022). "Hypocalcaemia stimulates increased PTH production by the parathyroid glands and elevated phosphate levels stimulate fibroblast growth factor 23 (FGF23) secretion by osteocytes." (PMID 31240395, 2020). "We examined in vivo the impact of FGF23 on the Ca2+/PTH relationship during normocalcemia and acute hypocalcemia in the rat and demonstrated that FGF23 has an inhibitory tonus on PTH secretion, when plasma Ca2+ is within the normal range." (PMID 33233840, 2020).
Hypocalcemia (continued). "Secretion of fibroblast growth factor 23 (FGF23) and parathyroid hormone (PTH) are increased to prevent accumulation of P and hypocalcaemia." (PMID 33374582, 2020). "Elevations in fibroblast growth factor 23 (FGF23) and increased secretion of parathyroid hormone (PTH) help to prevent the accumulation of phosphate and hypocalcemia." (PMID 30513703, 2018). "In acute hypocalcemia, when increased PTH secretion is needed to restore the calcium homeostasis, this inhibitory effect of FGF23 is abolished." (PMID 29063159, 2018). "In hypocalcemia, when increased PTH secretion is needed to restore the calcium homeostasis, this inhibitory effect of FGF23 is abolished." (PMID 29063159, 2018). "Wistar rats were allocated to treatment with intravenous recombinant FGF23 and inhibition of the FGF receptor in the setting of normocalcemia and acute hypocalcemia." (PMID 29063159, 2018). "Second, an acute increase in PTH, potentially triggered by transient hypocalcemia during TPE, may have stimulated rapid FGF-23 production." (PMID 40663633, 2026). "It was shown that phosphate-induced increments of FGF23 are dependent on calcium, and in an experiment in Wistar rats, FGF23 did not increase at all in a setting of hypocalcemia upon exposure to phosphate." (PMID 31505780, 2019). "FGF23 is upregulated by PTH and 1,25(OH)2D and downregulated by hypocalcemia." (PMID 27775655, 2016). "Studies in uraemic rats support this finding: in the presence of hypocalcaemia FGF23 production was not increased by low calcitriol or high PTH levels." (PMID 25543193, 2015). "Finally, in advanced CKD, hyperphosphatemia and hypocalcemia is present because the marked reduction of glomerular filtration makes FGF23 and PTH non-operative." (PMID 30909513, 2019). "Recent work has shown that there may be a threshold effect of serum calcium on FGF23 regulation, such that FGF23 is not stimulated when the calcium level is very low (essentially because this would reduce calcitriol and further aggravate hypocalcaemia)." (PMID 25543193, 2015). "In spite of these high FGF23 levels, rFGF23 had no suppressive effect on PTH levels during hypocalcemia." (PMID 29063159, 2018). "However, during acute hypocalcemia, where increased PTH levels are necessary to reverse hypocalcemia, no inhibitory effect of FGF23 on PTH secretion was observed." (PMID 30927339, 2019). "Therefore, the aim of the present investigation was to study the impact of FGF23 on the Ca2+/PTH relationship in vivo under conditions of normocalcemia and hypocalcemia." (PMID 29063159, 2018).
anemia (101 papers, 2012 to 2026). A reduction in the number of red blood cells, the amount of hemoglobin, and/or the volume of packed red blood cells. "This narrative review aims to describe the emerging complex relationships between anemia, anemia-related factors, FGF-23, and other relevant molecules implicated in the pathogenesis of CKD-MBD, defining a “kidney–bone marrow–bone axis”." (PMID 39684548, 2024). "Consistent with these pre-clinical studies, in a large cohort of adult patients with CKD (the Chronic Renal Insufficiency Cohort), increased baseline concentrations of total FGF23 were independently associated with both prevalent and incident anemia." (PMID 37752381, 2024). "FGF-23 promotes anemia and systemic inflammation and has been associated with poor outcomes in CKD patients." (PMID 39684548, 2024). "Multiple linear regression modeling was performed to evaluate the association between anemia and total FGF23." (PMID 37752381, 2024). "In the 185 study participants with both total and intact FGF23 measurements, in unadjusted analyses, the magnitude of the association between anemia and total FGF23 was more pronounced than the magnitude of the association between anemia and intact FGF23." (PMID 37752381, 2024). "Animal studies support inverse associations between FGF-23 levels and iron availability and erythropoietic activity and clinical, prospective trials have coupled total FGF-23 levels to the risk of incident anemia." (PMID 36698076, 2023). "The findings of a prospective cohort study of 3,869 patients with non-dialysis CKD indicated significant associations between elevated FGF23 levels and anemia." (PMID 37605118, 2023). "Clinical data in non-dialysis CKD patients indicated the association between total FGF23 levels with the risk of incident and prevalent anemia, and a decline in hemoglobin over time." (PMID 36831276, 2023). "Epidemiological studies have found that FGF-23 is independently associated with anemia, and animal studies have reported possible causal mechanisms." (PMID 35602513, 2022). "As serum P and FGF23 concentrations potentially contribute to the risk of anemia, we studied the association between the hemoglobin levels and both P and iFGF23 levels." (PMID 36432528, 2022). "The underlying mechanism comprises not only FGF23 induced myocardial toxicity but also aggravating inflammation, immunologic dysfunction, anemia, etc.." (PMID 35801203, 2022). "In CKD patients, associations of FGF23 serum concentrations with hemoglobin levels and the presence of anemia have been described." (PMID 32823844, 2020). "Anemia and elevated FGF23 are each highly associated with poor outcomes in patients with CKD, including increased odds for death and severe morbidity." (PMID 32476270, 2020). "It was also shown in non‐dialysis patients with CKD that circulating FGF23 is associated with anemia." (PMID 32476270, 2020). "Clinical investigations have demonstrated significant associations between increased serum FGF23 levels, the longitudinal decline in hemoglobin levels and the overall risk incidence of anemia." (PMID 31461904, 2019). "In summary, abnormalities in mineral metabolism and the metabolic milieu are associated with chronic inflammation and anemia, and FGF23 is a risk factor in this context." (PMID 31461904, 2019). "A prospective pathomechanism coupling elevated serum FGF23 levels with CKD-associated anemia and cardiovascular injury is its strong association with chronic inflammation." (PMID 31461904, 2019). "When FGF23 was treated as a continuous variable, a significant association between FGF23 and anemia remained unaltered (HR for every 1 log increase, 1.17; 95% CI, 1.07–1.29; P = 0.001)." (PMID 29740119, 2018). "In the fully adjusted model, the risk of developing anemia was significantly higher in the third (HR, 1.66; 95% CI, 1.11–2.47; P = 0.01) and fourth (HR, 1.84; 95% CI, 1.23–2.76; P = 0.003) quartile of FGF23 compared with the first quartile." (PMID 29740119, 2018).
anemia (continued). "When FGF23 quartiles were entered as a categorical variable in the model, the highest quartile of FGF23 was significantly associated with anemia compared with the lowest quartile (OR, 1.72; 95% CI, 1.19–2.50, P = 0.004)." (PMID 29740119, 2018). "After rigorous adjustment of confounders, log-transformed FGF23 was independently associated with anemia (OR, 1.14; 95% CI, 1.04–1.24, P = 0.01)." (PMID 29740119, 2018). "Several cross-sectional studies have suggested a possible association between FGF23 and anemia in these patients." (PMID 29740119, 2018). "Multivariate logistic regression showed that log-transformed FGF23 was independently associated with anemia (odds ratio [OR], 1.14; 95% confidence interval [CI], 1.04–1.24, P = 0.01)." (PMID 29740119, 2018). "Although there are well-established risk factors for anemia, our study suggests that FGF23 can also be a useful biomarker of incident anemia in patients with nondialysis CKD." (PMID 29740119, 2018). "Further studies are required to clarify the mechanism for FGF23-associated anemia in these patients." (PMID 29740119, 2018). "An in-depth analysis on the association between FGF23 levels and the development of anemia was performed using multivariable Cox regression models." (PMID 29740119, 2018). "The present clinical study aimed to assess associations between anemia, iron metabolism and FGF23 in hemodialysis (HD) patients." (PMID 28475601, 2017). "This association remained significant after adjustment for demographic parameters, CKD-specific factors, inflammation, ESA use, iron supplementation, and mineral metabolism parameters, suggesting a robust association between anemia and higher total FGF23 values." (PMID 37752381, 2024). "In the present study, we evaluated associations between anemia and FGF23 in a large cohort of pediatric patients with CKD, hypothesizing that anemia is associated with increased circulating FGF23 concentrations." (PMID 37752381, 2024). "In the subgroup that had measurements of both total and intact FGF23 (n = 185), in fully adjusted models, anemia was significantly associated with higher total FGF23 (standardized β (95% CI) 0.16 (0.04, 0.27), p = 0.008) but not intact FGF23 (standardized β (95% CI) 0.02 (−0.12, 0.15), p = 0.81)." (PMID 37752381, 2024). "In the present study, we sought to evaluate how contributory anemia is to elevated FGF23 levels in a cohort of pediatric patients with CKD, hypothesizing that anemia is associated with increased circulating FGF23 concentrations." (PMID 37752381, 2024). "In multivariable linear regression modeling, anemia was independently associated with higher total FGF23, after adjustment for demographic, kidney-related, mineral metabolism, and inflammatory covariables (standardized β (95% confidence interval) 0.10 (0.04, 0.17), p = 0.002)." (PMID 37752381, 2024). "The association between phosphate and anemia shown in this study may be mediated by factors other than FGF23." (PMID 37605118, 2023). "Clinical studies have shown an association between FGF23 and anemia." (PMID 37605118, 2023). "Interestingly, several clinical studies involving patients with CKD stages 3–4 and 2–4, along with patients undergoing hemodialysis, have demonstrated an association between FGF23 and anemia." (PMID 37605118, 2023). "In the studies of Akalin and Honda, higher levels of P could have masked the true association between FGF23 and anemia." (PMID 36432528, 2022). "Furthermore, higher FGF23 was associated with evidence of more advanced anaemia and renal dysfunction, as well as with evidence of systemic inflammation." (PMID 32935918, 2020). "Additionally, disturbances in erythropoiesis in kidney disease such as anemia, deficiency and supplementation of erythropoietin and iron, all have an effect on FGF23 synthesis and degradation resulting in increased plasma levels of FGF23." (PMID 33233840, 2020). "We then performed in-depth analyses to clarify the association between FGF23 and anemia." (PMID 29740119, 2018).